MYC (MYC proto-oncogene, bHLH transcription factor)
Diseases named in the same sentence as MYC in open-access papers (continued):
Sharing a sentence is not in itself a finding about the gene and the disease.
urothelial carcinoma (10 papers, 2008 to 2025). A malignant neoplasm derived from the transitional epithelium of the urinary tract (urinary bladder, ureter, urethra, or renal pelvis). "While gene amplification may underlie MYC protein overexpression in other cancer types, these studies suggested that MYC amplification is an uncommon cause of MYC protein overexpression in urothelial carcinoma providing evidence for the importance of other mechanisms of MYC dysregulation in UBC." (PMID 39031286, 2024). "It was also described that most urothelial carcinomas with protein overexpression lack MYC amplification, and only some of the MYC amplified tumors overexpress MYC protein." (PMID 39031286, 2024). "MYC amplifications were also seen in 0.6% of pTa, 4% of pT1, 5.5% of pT2–4, as well as in 0.8% of G1, 1.7% of G2 and 4.7% of G3 urothelial carcinomas, with an overall amplification rate of 2.9%." (PMID 39031286, 2024). "A positive feedback loop has also been described between C/EBPδ and MYC which co-amplify in urothelial carcinoma (UC) to promote a metabolic shift from oxidative phosphorylation towards glycolysis." (PMID 39273396, 2024).
Alzheimer disease (9 papers, 2012 to 2026). A progressive, neurodegenerative disease characterized by loss of function and death of nerve cells in several areas of the brain leading to loss of cognitive function such as memory and language. "In Alzheimer’s disease, specific transcription factors, such as MYC and CTNNB1, are altered in inhibitory neurons, leading to altered communication patterns between microglia and neurons." (PMID 40292254, 2025). "This study aimed to explore the effect of microRNA (miR)-146a inhibition on regulating cell apoptosis, total neurite outgrowth, inflammation, and STAT1/MYC pathway in Alzheimer's disease (AD)." (PMID 33729395, 2021). "The miRNA hsa-miR-146a is crucial for the progression of Alzheimer’s disease and functions through the hsa-miR-146a/STAT1/MYC pathway." (PMID 28970833, 2017). "Notably, even in the absence of stress, c-MYC assembles into soluble amyloid-like oligomers in human cancer tissues and Alzheimer's disease brains." (PMID 41959199, 2026).
gallbladder cancer (9 papers, 2014 to 2025). "For example, MINCR upregulates the expression of EZH2 by sponging miR-26a, which further enhances the MYC/miRNA/EZH2 axis in gallbladder cancer." (PMID 37215074, 2023). "Especially, MYC and the Wnt/β-catenin pathway might be a potential therapeutic targets of gallbladder carcinomas with high expression of FAM83H/ZNF16 because MYC is a transcriptional regulator of FAM83H and FAM83H stabilizes β-catenin." (PMID 32460791, 2020). "Furthermore, a positive pairwise correlation among PLGF, c-MYC, and miR-19a expression in gallbladder cancer (GBC) tissues has been displayed; this finding confirmed that the PLGF/c-MYC/miR-19a axis is involved in tumor progression of the gastrointestinal tract." (PMID 33946718, 2021).
leiomyoma (9 papers, 2007 to 2026). A well-circumscribed benign smooth muscle neoplasm characterized by the presence of spindle cells with cigar-shaped nuclei, interlacing fascicles, and a whorled pattern. "Noteworthy, in leiomyomas, a decreased expression of MYC and NR5A2 in tumors compared to the corresponding myometrium has also been observed." (PMID 36140779, 2022). "Fib-EXO increased the expression of vimentin, EZH2, DNMT1, TGF-β3, and c-MYC, and phosphorylated p65 protein, reduced COL1A1 and COL3A1 expression, and decreased miR-133a, miR-29, and miR-200c while increasing miR-21 in cultured myometrial smooth muscle cells, mirroring changes observed in fibroids." (PMID 42008339, 2026). "PTSMT have an increased MYC expression and low levels of THBS1 but no up-regulation of the miR 17~92 cluster, including miR-19a (in PTSMT mean relative expression level 0.02 versus 0.03 in leiomyomas) and miR-19b (mean 1.63 in PTSMT versus 2.23 in leiomyomas)." (PMID 24398114, 2014).
malignant glioma (9 papers, 2003 to 2024). A grade III or grade IV glioma arising from the central nervous system. "However, literature data about the association of B7H3 and the MYC gene are limited and concern only malignant gliomas in which a knockout of the B7H3 gene inhibits MYC expression." (PMID 37370746, 2023).
metastatic carcinoma (9 papers, 2011 to 2025). A carcinoma which has spread from the original site of growth to another anatomic site. "IGF2BPs are overexpressed in metastatic cancers, and their expression is associated with that of important oncogenes, such as MYC." (PMID 40507925, 2025). "The mutual polyploidy-c-MYC-bivalent genes-associated protein network was organized by gene-hubs engaged in both embryonic development and metastatic cancer including driver (proto)-oncogenes of viral origin." (PMID 33228223, 2020). "Goblet-like cells were localized with epithelial cells (gray) in treatment-naive cancer (Colon 1) but also co-localized with malignant cells with the MYC signature in metastatic cancer (Liver metastasis 2)." (PMID 38084922, 2023). "Discordance of c-MYC mRNA overexpression between the primary and distant metastatic cancer was detected in 25.6 % (45 out of 176) of cases, and discordance between the primary and lymph node metastatic cancer was observed in 30.6 % (34 out of 111) of cases." (PMID 27619912, 2016). "Discordance of c-MYC protein overexpression between the primary and distant metastatic cancer was detected in 45.5 % (80 out of 176) of cases, and discordance between the primary and lymph node metastatic cancer was observed in 31.5 % (35 out of 111) of cases." (PMID 27619912, 2016). "Besides, overexpression of c-MYC also leads to many cancers and it could be used as a possible target for therapeutic intervention in metastatic cancers." (PMID 33816287, 2021). "Interestingly, several well-known oncogenes linked to aggressive and metastatic cancer phenotype, including CXCL1, CXCL2, MYC, and BMP4, were included in this gene get, suggesting that BRD4 and STAT3 can coordinately regulate the oncogenic enhancer activity to promote tumor progression." (PMID 34290255, 2021).
metastatic colorectal cancer (9 papers, 2016 to 2023). "Gene expression, cancer cell migration, invasion, and proliferation were studied after siRNA-mediated knockdown of CCAT1, CCAT2, and MYC in metastatic colorectal cancer cell lines Colo205 and HROC277Met2." (PMID 37347737, 2023). "Knockdown of CCAT1, CCAT2, and MYC resulted in increased migratory and invasive potential in metastatic colorectal cancer cell lines." (PMID 37347737, 2023). "Recent findings on the differences between primary and metastatic colorectal cancer based on transcriptomic data indicate that metastasis is characterised by reduced EMT but increased MYC pathway activity." (PMID 33498690, 2021). "Moreover, we were able to demonstrate the direct impact of CCAT1, CCAT2, and MYC on metastatic colorectal cancer cell migration by affecting targets of Wnt signaling, including the upregulation of PPARD." (PMID 37347737, 2023). "Alterations in the transcriptional factor c-MYC could be involved in the anti-EGFR resistance in metastatic colorectal cancer (mCRC)." (PMID 32164324, 2020). "A study on immunohistochemical staining for metastatic colorectal cancer found that patients with a high expression level of c-MYC had a significantly lower progression-free survival time and overall survival than those with reduced c-MYC expression." (PMID 33193630, 2020).
metastatic melanoma (9 papers, 2016 to 2023). A melanoma that has spread from its primary site to another anatomic site. "Our analysis highlighted the potential clinical usage of MYC inhibitors in treating metastatic melanoma patients." (PMID 34122516, 2021). "Given that the TI signature reflected poor clinical outcomes of metastatic melanoma patients, we sought for potential drugs that could inhibit the function of the genes in the TI signature which was annotated as the MYC-related pathway." (PMID 34122516, 2021). "Using the same iPSC markers, we have also shown the presence of two CSC subpopulations within head and neck metastatic malignant melanoma (HNmMM): an OCT4+/SOX2+/KLF4+/c-MYC+ CSC subpopulation within the TNs, and another in the PTS with NANOG present only in two of the 20 cases studied." (PMID 32850316, 2020). "In contrast to the correlative association between MITF and c-MYC in single-cell RNA-seq data sets on metastatic melanoma, preliminary data indicate that expression of c-MYC appears to be decoupled from MITF at the protein level in bulk MITF-low tumor cells and TERT-immortalized melanocytes." (PMID 30651597, 2019). "We demonstrate strong enrichment of ecDNA molecules containing EGFR, FGFR2 and MYC from human cancer cells and NRAS ecDNA from human metastatic melanoma with acquired therapeutic resistance." (PMID 36253572, 2022). "Cisplatin-resistant tumor cells, e.g., NIH3T3 cells and metastatic melanoma cells, express high levels of the c-MYC protein, an observation which suggests that c-MYC overexpression contributes to chemoresistance." (PMID 27419628, 2016).
oesophageal cancer (9 papers, 2008 to 2025). "In addition, c-MYC amplified oesophageal cancer cell lines were observed to be synthetically lethal with silencing of BTK." (PMID 35448150, 2022). "Furthermore, BTK-inhibition with ibrutinib, an irreversible selective inhibitor of BTK, has been shown to directly inhibit growth of c-MYC and/or HER-2 amplified oesophageal cancer cell lines with downregulation of c-MYC and p-ERK, as well as corresponding cell-cycle arrest." (PMID 35448150, 2022). "c-MYC and/or HER-2 amplified oesophageal cancer models have demonstrated sensitivity to BTK inhibition with ibrutinib." (PMID 35448150, 2022). "In conclusion, the expression patterns of c-MYC, MAX and the MAD family were shown to be deregulated in the oesophageal cancer model." (PMID 18493233, 2008). "Furthermore, while the c-MYC and/or HER2 oesophageal cancer cell lines were sensitive to ibrutinib at nanomolar concentrations, cell lines do not account for histological obstacles posed by the complex architecture of human cancers." (PMID 35448150, 2022).
papillary thyroid carcinoma (9 papers, 2016 to 2026). "This indicates that introduction of c-MYC induces the tumor cells to gain a new phenotype, i.e. the columnar structure, which appears to be more malignant and hence a signature for the appearance of papillary carcinomas in the advanced stages of tumor progression." (PMID 29464089, 2018). "The translational significance of these findings is highlighted by the consistent overexpression of SIRT1 in follicular and papillary thyroid carcinomas, positively correlates with c-MYC protein levels and stabilizes c-MYC." (PMID 30319549, 2018).
pineoblastoma (9 papers, 2020 to 2025). Pineoblastoma is a rare, malignant type of supratentorial primitive neuroectodermal tumor (sPNET), found mainly in children (less than 10% of cases are reported in adults), and located in the pineal region of the brain but that can metastasize along the neuroaxis. "Understanding the role of FOXR2/MYC in pineoblastoma can help in developing targeted therapies aimed at these specific genetic alterations." (PMID 39866234, 2025). "CNS_025, classified as a pineoblastoma MYC/FOXR2‐activated subtype, showed broad 8 chromosomal gain involving the MYC locus, similar to other tumours from this molecular subtype." (PMID 41033792, 2025). "Additionally, Pineoblastoma-FOXR2/MYC and CNS-NB-FOXR2 represent distinct molecular subgroups within the broader category of pediatric brain tumors, each with unique genetic characteristics and implications for treatment and prognosis." (PMID 39866234, 2025). "In the reported German cases, biological relationship to pineoblastoma (PIN MYC/FOXR2) was found." (PMID 38253790, 2024). "Pineoblastoma was is divided into Pineoblastoma, MYC/FOXR2 activated, Pineoblastoma, RB1-altered, Pineoblastoma miRNA-1 and miRNA-2 base on a desirable diagnostic method of DNA methylation profiling." (PMID 38459438, 2024). "Pineoblastomas are described as having four molecular subgroups in the latest WHO classification and ATRTs have been divided into the tyrosinase (TYR), MYC, and SHH subgroups." (PMID 37835574, 2023). "In the context of these recent discoveries, the World Health Organization’s 2021 classification for pineoblastoma defined four molecular subtypes: miRNA processing altered 1, miRNA processing altered 2, RB1-altered, and MYC/FOXR2-activated, each with a distinct prognosis." (PMID 37444483, 2023).
seminoma (9 papers, 2017 to 2025). A radiosensitive malignant germ cell tumor found in the testis (especially undescended), and extragonadal sites (anterior mediastinum and pineal gland). "Other malignancies with a high prevalence of c-MYC pathway mutations were HNSC HPV- (85%), TCGT seminoma (72%), and high CN UCEC (70%)." (PMID 35801728, 2022). "However, within our pre-diagnostic data, we did not see MYC or SP1 as eigengenes in any of the seminoma or non-seminoma modules." (PMID 39809819, 2025). "In particular, the transcription factor-target gene pairs, MYC and SP1, were found to be common eigengenes in both seminoma and non-seminoma, as well as the miRNA miR-182-5p32." (PMID 39809819, 2025).
Wilms tumor (9 papers, 2010 to 2024). An embryonal neoplasm characterized by the presence of epithelial, mesenchymal, and blastema components. "Since these samples have low MYC expression but relatively high target gene set activity, the plot suggests that MYC target genes may be activated in Wilms tumor by other regulators, or the measurements of MYC RNA level in these samples may not reflect the underlying true MYC protein level." (PMID 26350211, 2016). "In preclinical studies of Wilms tumor, the bivalent BRD4 inhibitor AZD5153 led to reduced MYC levels in cell lines derived from anaplastic and non-anaplastic Wilms tumor, and inhibited tumor growth in patient-derived xenografts." (PMID 39766049, 2024).
atypical teratoid rhabdoid tumor (8 papers, 2019 to 2026). Atypical teratoid rhabdoid tumor (ATRT) is a highly malignant central nervous system (CNS) rhabdoid tumor (RT) found almost exclusively in children. "An atypical teratoid rhabdoid tumor (ATRT) is caused by loss of the INI1 subunit and has been shown to be linked to aberrant activation of signaling pathways dependent on two TFs–MYC or GLI1." (PMID 40065228, 2025). "Atypical teratoid rhabdoid tumors (ATRT) are divided into MYC, TYR and SHH subgroups, suggesting diverse lineages of origin." (PMID 37863903, 2023). "The atypical rhabdoid teratoid tumours (AT/RT) were further subclassified into three subtypes: SHH (3, 50%), MYC (2, 33.3%) and TYR (1, 16.7%)." (PMID 41033792, 2025). "Atypical teratoid rhabdoid tumor (ATRT) models represented both Sonic hedgehog (SHH; n = 3) and MYC (n = 3) subgroups, with two models unclassified." (PMID 31693904, 2019).
chondrosarcoma (8 papers, 2018 to 2024). A malignant cartilaginous matrix-producing mesenchymal neoplasm arising from the bone and soft tissue. "MYC amplification can be used as a marker of prognostic importance in chondrosarcoma, associated with a worse prognosis." (PMID 37546405, 2023). "Our data revealed a significant increase in cMyc (MYC) and cyclin D1 expression after both X-rax and C-ion IR in chondrosarcoma cells." (PMID 38892366, 2024). "The NDCS1 cell line is most sensitive towards ML792 and the CH3573 cell line is among the least sensitive cell lines in our panel, indicating a lack of correlation between c-MYC levels and sensitivity towards SUMO E1 inhibition in chondrosarcoma." (PMID 34359724, 2021).
depression (8 papers, 2016 to 2025). "Taken together, MYC might initiate the carcinogenesis of depressed neoplasms at the early stage, and subsequently, CCNA1 and BIRC7 might promote its invasiveness and further migration." (PMID 32532105, 2020). "Removal of clock repression by MYC may play a role in the interaction of SD with depression and further investigation of these potential mechanisms is warranted." (PMID 31852885, 2019). "Other studies that investigated DNA methylation signatures of depression in discordant monozygotic twins study design implicated epigenetic changes in VDR26, HOXB7, CACNA1C, STK32C, NR1C3, and MYC genes among others, but not in KLK8 or DAZAP247,108,117,118." (PMID 31477683, 2019).
Insulin resistance (8 papers, 2006 to 2024). Increased resistance towards insulin, that is, diminished effectiveness of insulin in reducing blood glucose levels. "Of note, MYC modulates the inflammatory response, induces insulin resistance, and regulates intestinal dysbiosis." (PMID 38510176, 2024). "Max interactor protein, MXI1 (gene L07648) competes for MAX thus negatively regulates MYC function and may play a role in insulin resistance." (PMID 17217525, 2006).
lentivirus infection (8 papers, 2015 to 2025). Virus diseases caused by the Lentivirus genus. "RNA interference and lentivirus infection showed a positive correlation between the expressions of c-MYC and BCYRN1." (PMID 25866480, 2015).
mesothelioma (8 papers, 2016 to 2025). A usually malignant and aggressive neoplasm of the mesothelium which is often associated with exposure to asbestos. "Therefore, despite the absence of YAP track in the Cistrome DB of A549 cells, we assume that YAP binds PTEN promoter since a YAP peak overlapping with TEAD4, YY1 and MYC is present in the mesothelioma cell line H2052." (PMID 39455556, 2024). "In support of this, a decrease in c-MYC and NOXA expression is involved in the acquired resistance of mesothelioma cells to bortezomib." (PMID 29755650, 2018).
neuroendocrine carcinoma (8 papers, 2014 to 2024). A malignant neuroendocrine neoplasm composed of cells containing secretory granules that stain positive for NSE and chromogranin. "In addition, although there are only two cases of neuroendocrine carcinoma, nuclear expression of FAM83H in neuroendocrine carcinoma might be related to the MYC-FAM83H relationship because it has been reported that MYC drives progression of neuroendocrine carcinoma." (PMID 32564009, 2020). "Here, we investigated whether MDM2 upregulates MYC as well as MYCN in selected neural and neuroendocrine cancers." (PMID 33425720, 2020).
nut midline carcinoma (8 papers, 2017 to 2023). A rare, highly aggressive and lethal carcinoma that affects children and young adults. "The development of NUT carcinoma might be associated with mutation of MYC, p63, and MED24 genes and the Wnt, MAPK, and PI3K signaling pathways." (PMID 34527578, 2021). "NUT carcinomas show frequent reactivity to epithelial markers (various cytokeratins and rarely Claudin-4), SOX2, and MYC antibodies." (PMID 34898574, 2021). "However, SOX2 and MYC are not specific stains for NUT carcinoma." (PMID 34898574, 2021).